CXCL9 (C-X-C motif chemokine ligand 9)
Diseases named in the same sentence as CXCL9 in open-access papers (continued):
Sharing a sentence is not in itself a finding about the gene and the disease.
tumor (continued). "In addition, zeste homolog 2 (EZH2)-mediated histone lysine methylation and DNA methyltransferase-1 (DNMT-1)-mediated DNA methylation suppressed the production of CXCL9 and CXCL10 respectively, and then inhibited T-cell tumor homing." (PMID 35493527, 2022). "To determine whether CYLD exerts a similar effect on tumor-intrinsic chemokine production as SPATA2, we transiently knocked down CYLD by RNAi and measured CXCL9, CXCL10, and CXCL11 secretion." (PMID 36531014, 2022). "We further analyzed the quantity of CD3 + T and NK cells out of all cells in the tumor samples and observed that CXCL10, and CXCL9 levels were significantly correlated with the number of tumor infiltrating CD3 + T cells; CXCL10 levels also correlated with the number of tumor infiltrating NK cells." (PMID 35927313, 2022). "However, contrary to what was mentioned in the part of T lymphocytes, CXCL9 and CXCL10 here induce tumor invasion indirectly." (PMID 35935996, 2022). "Neither chemokine expression nor tumour-infiltrating immune subsets were affected by Cxcl9 or the anti-PD-L1 treatment in this model." (PMID 35314795, 2022). "In addition, the immunoregulatory effect of CXCL9, CXCL10, and the CXCL11/CXCR3 axis on tumor sites to promote antitumor immunity has been used as a new tumor therapeutic target." (PMID 35754838, 2022). "Indeed, our data from the characterization of CXCL9 and CXCL10 in the tumor location appears to be higher." (PMID 35459734, 2022). "Furthermore, the expression levels of CXCL9, CXCL10, CXCL11, and their receptor CXCR3, which perform anti-tumor roles in ICI treatment, were found to have increased in PTPRD/PTPRT mutant cancer patients." (PMID 36248841, 2022). "Compared with WT mice, the expression of CXCL9 in tumor derived leukocytes from STING-/- mice was also not altered by the I.T. treatment of either nanovaccine or PC7A alone." (PMID 35623658, 2022). "In addition, many T cell signatures have been reported to be predictive for anti-PD1 response in a variety of tumor types, including cytolytic, T cell IFN-γ-related mRNA profiles, the chemokine CXCL9, CD8A, and an antagonistic inflammatory phenotype." (PMID 34534438, 2021). "Thus, further investigation of the roles of the CXCL9/CXCL10/CXCL11-CXCR3 signaling is necessary for understanding its regulatory functions, particularly in a tumor environmrnt." (PMID 33407095, 2021). "Importantly, two-way ANOVA demonstrated a significant interaction effect in all markers except Cxcl1, Cxcl9, and Cxcl10, demonstrating the divergent effects that DOX has on cardiac inflammatory markers in tumor-bearing compared to tumor-free mice." (PMID 34445729, 2021). "In colorectal cancer, the lack of METTL3 or METTL14 increases cytotoxic tumor-infiltrating CD8+ T cells; enhances the production of interferon- (IFN-) γ, CXCL9, and CXCL10; and promotes the recruitment of CD8+ and CD4+ effector T cells that inhibit tumor growth." (PMID 34858499, 2021). "Thus, the addition of both ASA and low-dose IL-2 to the OCDC-Bev-Cy combinatorial regimen induced a Th1-polarizing sera chemokine profile, particularly CXCL9 that was conducive for the recruitment of CD3+ and CD8+ TILs for tumor control." (PMID 33723260, 2021). "Moreover, in an explorative response prediction model, the combination of protein markers (CXCL9, CXCL10, IL-15, CASP8, and ADA) resulted in higher accuracy in predicting response than tumor PD-L1 expression or each protein assayed individually." (PMID 34206510, 2021). "Certain proinflammatory factors, such as CXCL9, CXCL10, and CXCL16, promote the trafficking of immune cells into the tumor, increase leukocyte chemoattraction and extravasation, and induce tumor surface expression of PD-L1, MHC-I, NK cell ligand, and Fas (CD95) [10,41,57,]." (PMID 34247198, 2021). "Tumor-infiltrating neutrophils can support adaptive immune responses by recruiting T cells to tumor sites via the secretion of chemokines, such as CCL5, CCL20, CXCL9, CXCL10 and CXCL11." (PMID 34572138, 2021).
tumor (continued). "Anti-tumor immune response by IFN-γ can also be elicited by recruitment of additional effector cells, namely NK cells and M1 macrophages to the TME, facilitating T-cell homing through CXCL9 and CXCL10 chemokines, and via enhanced CD8+ cytotoxicity in the TME." (PMID 34012451, 2021). "The accumulated evidences indicated that M1 conditioned medium (M1 CM) could inhibit tumor growth via TNF-α, CXCL9, IFN-γ, or CCL3 in different types of cancers." (PMID 33175182, 2021). "Peak expression was observed at the 20 μg free CDN dose while the higher dose of 100 μg that was required for distal non-injected tumor control and led to immune ablation resulted in decreased CXCL9 production." (PMID 33888863, 2021). "Finally, other approaches point to overexpressing some of the chemokine receptors involved in T cell trafficking to inflammatory sites, such as CXCR3, owing to expression of its ligands, CXCL9 and CXCL10, in the GBM tumor microenvironment (TME)." (PMID 33746981, 2021). "The correlation between CXCL9 and T cells was higher in MSI and present in all tumor samples." (PMID 34072037, 2021). "CAF with tumor-promoting functions secrete growth factors (HGF, IGF1, CTGF, PDGF, VEGF, LIF), cytokines (IL-1, IL-4, IL-6, IL-8, IL-10, TGF-β), and chemokines (CCL2, CCL5, CXCL5, CXCL9, CXCL10, CXCL12), WNT5α, and bone morphogenic protein 4 (BMP4), which promote tumor progression." (PMID 35008832, 2021). "Moreover, their cognate ligands, including CCL2, CCL3, CCL4, CCL5, CXCL9, CXCL10, and CXCL11, are often upregulated in a range of different tumour types." (PMID 34885108, 2021). "Along with this, early studies indicated that either overexpression of CXCL9 by cancer cell lines, or direct injection of CXCL10 to the tumor site, or targeted gene therapy of CXCL10, may limit cancer development." (PMID 34944943, 2021). "The expression of CXCL9/10/12/14 was significantly positively correlated with not only the infiltration and biomarkers’ expression of various tumor-infiltrating immune cells but also the abundance of chemokines and their receptors." (PMID 34085699, 2021). "In addition to CXCL10, the injection of anti-IFN-γ also significantly impaired the production of CXCL9 and CCL5 in the tumour microenvironment compared to isotype antibody-treated tumours." (PMID 33925140, 2021). "Therefore, we determined the expression levels of CXCL-9, CXCL-10, CCL-17, and CCL-22 in tumor tissues." (PMID 34620867, 2021). "Moreover, the intraepithelial tumor-infiltrating lymphocytes recruited by tumor chemokine CCL5 release IFN-γ to activate TAMs and DCs to secrete CXCL9, which in turn establishes a positive loop effectively amplifying T cell recruitment in EOC." (PMID 34248988, 2021). "shows that CXCL9 activated STAT3 signaling in CD8+ T cells of PDAC cell, and suppression of STAT3 could recover the proliferation and secretion of anti-tumor cytokines of CD8+ T cells." (PMID 34367961, 2021). "Additionally, CXCL9 and CXCL10 are also expressed by M1-polarized TAMs and CXCL11 can be found on tumor vasculature." (PMID 34203660, 2021). "Our data thus demonstrate that treatment of some human GBM cells with GSK126 in vitro, results in a reversal of H3K27me3 that allows increased expression of CXCL9 and CXCL10 when induced by IFNγ leading to increased migration of T cells to tumor conditioned medium." (PMID 34336705, 2021). "In addition, we observed enhancement of not only CD8+ T cell infiltration but also DC infiltration and upregulation of CXCL9, CXCL10, GZMA, GZMB, and IFN-γ in Col6a1−/− tumor tissues compared with WT MCA205 tumor tissues." (PMID 34782761, 2021). "Additionally, the secretion of IFN-γ by Th1 cells can also promote CXCL9 and CXCL10 expression in the tumor microenvironment (TME) and therefore ensure the recruitment of CXCR3 expressing CD8+ T cells at tumor site." (PMID 34262562, 2021).
tumor (continued). "CCR5-CCL5 axis was induced to enhance NK cell infiltration in tumor tissue, and CXCR3 on NK cells also could interact with CXCL9, CXCL10, and CXCL11 from tumor cells." (PMID 33918941, 2021). "We found that treatment with SHP099 led to increased expression of three CXCR3 ligands, the chemoattractant cytokines CXCL9, CXCL10 and CXCL11 specifically in tumor cells in co-culture, with CXCL10 showing the most significant upregulation and magnitude of expression." (PMID 33446805, 2021). "The CXCR3/CXCL9-11 axis plays a key role in promoting the entrance of Th1 cells, CD8+T cells, and NK cells into the IME, thus producing a T cell inflammatory IME which has a strong anti-tumor effect." (PMID 35095920, 2021). "Several studies have shown that CXCL9 had both positive and negative effects; on the one hand, overexpression of CXCL9 has shown to reduce tumor progression by inhibiting angiogenesis." (PMID 33815462, 2021). "Among them, CXCL9 is crucial for recruiting immune T cells into the TME35, XCL2 plays a role in recruitment of DCs36, and CXCL13 can recruit both T cells and B cells into tumor tissues to enhance tumor immunity." (PMID 34556668, 2021). "Additionally, some other chemokines controlling T lymphocyte homing to peripheral tissues, such as CCL5, CXCL9, CXCL10, and CXCL11, were also highly expressed in tumours containing large numbers of tumour HEVs." (PMID 33917287, 2021). "Similarly, analyses in both the GEPIA2 (with 1,085 tumour samples and 291 normal samples) and UALCAN (with 1,097 tumour samples and 114 normal samples) databases showed lower CXCL9 expression in normal tissues." (PMID 34527583, 2021). "In our model, mice treated with an antibody to block the binding of CXCL10 and CXCL11 to CXCR3 (but not the binding of CXCL9 to CXCR3) were unable to control the growth of established tumours." (PMID 33925140, 2021). "Tumor growth factors (e.g., EGF, PDGF-α, PDGF-β, HGF, and GDF-15), chemotactic factors (e.g., CXCL9 and CCL-25), matrix metalloproteinases (MMP1, MMP3, and MMP9), and inflammatory cytokines (IL-1β, IL-2, and IL-7) were discovered in liver tumors to chemoattract MSCs." (PMID 34603454, 2021). "While all three CXCR3 ligands were elevated in niches with actively growing tumor populations, IP-10 (CXCL10; growing 2.2-fold, emergent 1.5-fold) was present at markedly higher absolute levels than that of MIG (CXCL9; growing 1.5-fold, emergent 1.4-fold) and I-TAC (CXCL11; emergent 1.4-fold)." (PMID 34123844, 2021). "The immune activation of IFN-γ on tumor cells is largely attributed to tumor cells, monocytes, endothelial cells, and fibroblasts inducing tumor cells to express MHC class I and secrete CXCL9, CXCL10, and CXCL11 to promote lymphocyte migration and inhibition of angiogenesis." (PMID 34795663, 2021). "Our current working hypothesis is that peripheral administration of CXCL10-Ig or CXCL9-Ig would induce the activity of CXCR3+ effector CD4+ T cells, effector CD8+ T cells, and NK cells that are then recruited to at the tumor sites to limit cancer." (PMID 34944943, 2021). "The expression of CXCL8, CXCL9, CXCL11, and CXCL13 was increased as the tumor stage increased." (PMID 33763130, 2021). "In response to interferons, macrophages are polarized and activated into pro-inflammatory classical M1 type that produces cytokines, such as interferon-γ (IFN-γ), tumor necrosis factor-α (TNF-α), IL-23, IL-12, CCL5, CXCL9, CXCL10, and CXCL5 and help destroy tumor cells via activating Th1 cells." (PMID 33925575, 2021). "cDC1s play a crucial role in the activation of anti-tumor immune responses, also acting locally in the TME, where, by producing the chemokines CXCL9 and CXCL10, they attract tumor-infiltrating T cells in the cDC1-rich areas and sustain local T cell restimulation." (PMID 34062821, 2021). "Indeed, CXCR3 signaling through interaction with CXCL9 and CXCL10 has been shown to play a relevant role in tumor homing of effector T cells." (PMID 33746981, 2021).
tumor (continued). "After contact with each other, T cells and tumor cells secrete CXCL9 and CXCL10, induced by INF-γ, with a positive feedback mechanism to increase the infiltration of immune cells (CD8+ T cells, NK cells, and macrophages) within the tumor." (PMID 33330629, 2020). "Similarly, for the representative values of the expression levels of genes involved in tumor-T cell interaction, we selected six genes (IFNGR1, PD-L1, CXCL9, IFNγ, PD-1, and CXCR3) and termed this group as an immune response predictor (IRP)." (PMID 32795913, 2020). "Thus, their corresponding ligands such as CCL5, CXCL9, CXCL10, and CX3CL1 effectively guide CD8+ CTL mobilization from regional lymph nodes to tumor tissues." (PMID 31991604, 2020). "Irradiation treatment can also upregulate the expression of CD70 on DCs, enhance the activation of T cells, induce the expression of chemokines CXCL-9, CXCL-10, CXCL-11 as well as CXCL-16, and attract antigen-specific T cells to infiltrate irradiated tumor regions." (PMID 32960261, 2020). "IFN-γ and other cytokines, such as CCL2, CCL23, CXCL9, and CXCL10 have anti-tumor roles." (PMID 32346605, 2020). "While patterns of CXCR2 in immune cells were not consistent with the patterns of immune cells induced by CXCL5, CXCR3 was highly expressed in T cells in the tumour microenvironment of PAAD tissue, which was in agreement with the induced patterns change of immune cells induced by CXCL9/10." (PMID 31913856, 2020). "In part, the lack of toxicity may be due to CXCR3‐expressing CAR T cells being unable to efficiently home and infiltrate into the cerebellum, as the cerebellum expressed negligible levels of Cxcl9 and Cxcl10 when compared to the HER‐2‐E0771 tumours." (PMID 31803974, 2020). "Interestingly we found the CXCL9, -10,-11/CXCR3 (fold change 9.5, 8, 14 and 2.5 with p = 0.0005–0.0001) axis to be significantly upregulated in the tumor tissue, promoting cancer cell proliferation and metastasis (autocrine axis)." (PMID 31960110, 2020). "Very recently Andy Luster and his group showed that anti PD-1 efficacy is reduced in CXCR3KO mice, and suggested that the interaction between CXCL9, largely produced by CD103+ dendritic cells (DC) at the tumor site, and CXCR3 on CD8+ T cells enhances anti PD-1 efficacy." (PMID 32547545, 2020). "In addition, CXCL9,−10,−11/CXCR3 network was confirmed to affect tumor resistance to checkpoint inhibitors by regulating immune cells activation." (PMID 32974144, 2020). "Gene expression profile can also assess the functional state of TILs: in a prospective setting, IMpower150 study of PDL-1 inhibitor atezolizumab used the biomarker CD8+ Teff gene signature, defined by PDL-1, CXCL9, and IFN-γ mRNA expression from baseline tumor tissue." (PMID 32670271, 2020). "As in the case of CXCL9, IRF5 (interferon regulatory factor 5) can bind to the promoter of CXCL13 and directly regulate its expression in mammary epithelial tumor cells leading to the infiltration of CD19+CXCR5+ B-cell and CD4+CXCR5+ T-cell to the tumor." (PMID 33304345, 2020). "Moreover, examination of cytokine/chemokine production in the tumor microenvironment revealed an increase in the levels of chemoattractive cytokines such as CCL3, CCL4, CCL5, CXCL9, CXCL10 and CXCL11." (PMID 32033490, 2020). "A failure in effector CD8+ T cells' traffic into melanoma tissue from tumor-draining lymph nodes in a mice model is mediated by the lack of chemokines CXCL9 and CXCL10 produced by CD103+ DCs." (PMID 32210957, 2020). "Treatment with Romidepsin, a bicyclic class 1 selective HDAC inhibitor, has been shown to increase the expression of CCL5, CXCL9, and CXCL10 in tumor cells, promoting T cell recruitment into the tumor site and boost T cell-mediated anti-tumor function in multiple lung tumor models." (PMID 32560120, 2020). "The increase in mRNA encoding expression of CXCR3, CXCL9 and CXCL10 (not CXCL11) as chemotactic chemokines suggests their involvement in the trafficking of anti‐tumor immune cells to the tumor site." (PMID 32821382, 2020).
tumor (continued). "CXCL9 plays a controversial role in tumor development and pathogenesis and exhibits both positive and negative prognostic values for different tumor types." (PMID 32714866, 2020). "A possible explanation behind the positive effect of eosinophils is their capacity to recruit cytotoxic T lymphocytes through CCL5, CXCL9, and CXCL10, to induce an anti-tumor phenotype in macrophages through TNFα and IFNγ and to normalize the tumor vasculature." (PMID 32793228, 2020). "To observe if injection of CXCL9 could induce cytotoxic T cell exhaustion, we, first of all, sorted the CD8+ cytotoxic T cells from PAAD tumour tissue of mice." (PMID 31913856, 2020). "For example, chemotactic cytokines, CXCL9 and CXCL10 may promote anti-tumor immune responses by recruiting NK and T cells into the tumor tissue thereby inhibiting angiogenesis." (PMID 32036449, 2020). "Depletion of CXCL9 and CXCL10 abrogated the anti-tumor activity of combined therapy." (PMID 33167311, 2020). "Expression of CXCL5, CXCL9, and CXCL10 was significantly negatively correlated with tumor purity." (PMID 33323542, 2020). "Moreover, DNMT1 represses the tumor production of T helper 1 (TH1)-type chemokines CXCL9 and CXCL10 and the impacts on effector T-cell trafficking into the tumor microenvironment." (PMID 32708698, 2020). "Moreover, CD103+ cDC1s are a major source of CD8+ T cell chemoattractants, including C-X-C motif chemokine ligand 9 (CXCL9) and CXCL10, in the tumor microenvironment (TME); these chemokines drive T cell recruitment and anti-tumor immunity." (PMID 31947933, 2020). "CEA-TCB-treated tumors displayed a clear upregulation of several pro-inflammatory cytokines and chemokines [MIPα (CCL3), CXCL10, CXCL13, CXCL9, IL-16, and I-TAC (CXCL11)], an increase in intra-tumor CD3+, CD4+, CD8+ T-cells that express high levels of 4-1BB, PD-1, and upregulation of GZMB." (PMID 33330050, 2020). "Indeed, the deletion of SHP-2 increases macrophage production of chemokine (C-X-C motif) ligand 9 (CXCL9) in response to IFN-γ and tumor cell-derived cytokines, promoting T cell infiltration into the tumor." (PMID 33003469, 2020). "Chemokines CXCL9 and CXCL10 direct effector T cell trafficking and tumor infiltration." (PMID 32170083, 2020). "For T cell chemotaxis into the tumor, the CXCR3/CXCL9,10,11 axis seems crucial." (PMID 33679726, 2020). "Although we do not exclude other potential tumor-intrinsic mechanisms, the increased levels of Cxcl9 within and around LLC-sh21 tumors would allow for increased T cell infiltration and trafficking into tumors." (PMID 31133614, 2019). "Eosinophils may promote antitumor immunity by recruiting CD8+ T cells to the tumor microenvironment via secretion of chemoattractants (CCL5, CXCL9, and CXCL10) and normalization of tumor vasculature, thereby allowing for increased effector T cell infiltration." (PMID 31730503, 2019). "Besides, several chemokines including CXCL9, CXCL10, and CXCL12 were upregulated by genome-wide transcriptional profiling of tumor-infiltrated PTL-CAR-T cells." (PMID 31511513, 2019). "Additionally, irradiation enhanced the homing of the antigen-specific T cells to tumor tissues via the increased release of CCL5, CXCL9, and CXCL11 from tumor cells." (PMID 31921127, 2019). "Notably, CD8+ T cells were recruited to the tumor tissue upon LIF blockade and this effect was dependent on CXCL9, since its neutralization prevented CD8+ T cell infiltration." (PMID 31186412, 2019). "Interestingly, CXCL9 and CXL10 were upregulated in BC tissue and were shown before to enhance the mobilization of cytotoxic T cells form regional lymph nodes to tumor tissues and to promote CTL-mediated tumor immunity." (PMID 31620367, 2019). "NK cells play a critical role in anti-tumor immunity and they could respond to several chemokine signals, including CCL3/CCL4/CCL5 via CCR5 and CXCL9/CXCL10 via CXCR340–42." (PMID 30718511, 2019).